AHR (aryl hydrocarbon receptor)
Diseases named in the same sentence as AHR in open-access papers (continued):
Sharing a sentence is not in itself a finding about the gene and the disease.
leiomyoma (3 papers, 2022 to 2023). A well-circumscribed benign smooth muscle neoplasm characterized by the presence of spindle cells with cigar-shaped nuclei, interlacing fascicles, and a whorled pattern. "TDO2 catalyzes the conversion of tryptophan to kynurenine, an aryl hydrocarbon receptor (AHR) ligand that we confirmed to be significantly elevated in mut-MED12 leiomyomas." (PMID 37607000, 2023). "It has been found that the tryptophan metabolism pathway may be related to cell survival and apoptosis, as the recent report showed that activation of the tryptophan–kynurenine–AHR pathway promotes leiomyoma cell survival and decreases apoptosis." (PMID 36612238, 2022). "The involvement of many proteins such as FN1, COL1A1, BMP7, CCND1, EZH2, HMGA2, AhR, and E2F1 shown in the protein–protein interaction networks are well known in leiomyoma pathogenesis; others, such as SOX2, REN, PPARG, ABCB1, and NR3C1 are novel and require further investigation." (PMID 36835153, 2023).
Liver Dysfunction (3 papers, 2013 to 2025). "Overall, these results show that the protective effect of an L-tryptophan-rich diet against HIE-induced liver dysfunction and disturbed homeostasis is mediated through an AhR-dependent pathway." (PMID 40277929, 2025). "Together, an L-tryptophan-rich diet can activate high-intensity exercise-induced liver dysfunction via the metabolite indole-3-acetic acid and AhR activation." (PMID 40277929, 2025). "Other AhR-related AOPs under development address the role of AhR activation for embryo or early life stage lethality, liver dysfunctions and liver tumors." (PMID 30870500, 2019). "Thus, we proposed that an L-tryptophan-rich diet improves high-intensity-exercise-induced liver dysfunction via the metabolite indole-3-acetic acid and AhR activation." (PMID 40277929, 2025). "However, the possibility cannot be ruled out that a cirrhosis-associated decrease in the expression of Arnt, with which AhR dimerizes, or other AhR cofactors may concur in decreasing the inducibility of CYP1A enzymes in severe liver dysfunction." (PMID 23626760, 2013). "Furthermore, we demonstrated that the protective effect of an L-tryptophan-rich diet was indeed abolished by the AhR inhibitor and IAA intervention can protect from excessive exercise-induced liver dysfunction in vivo and LPS-induced hepatocyte injury in vitro." (PMID 40277929, 2025).
male infertility (3 papers, 2019 to 2022). The inability of the male to effect fertilization of an ovum after a specified period of unprotected intercourse. "AHRR encodes a component in the aryl hydrocarbon receptor signaling cascade, which is involved in cell growth, and mutations in AHRR have been shown to associate with male infertility." (PMID 31494266, 2019). "Furthermore, Gu and colleagues showed that AHR polymorphism might be associated with variations of the levels of DNA fragmentation, BPDE-DNA adducts in the seminal fluid, and individual risk of male infertility." (PMID 31027257, 2019).
metastatic carcinoma (3 papers, 2013 to 2024). A carcinoma which has spread from the original site of growth to another anatomic site. "We examined the expression of AhR by immunohistochemistry in tissue microarrays (TMA) containing 192 specimens of clinically defined three stages of invasive breast cancer: node negative, node-positive and metastatic carcinoma." (PMID 25068070, 2013).
metastatic tumors (3 papers, 2013 to 2023). "While several candidates were identified with varying barcode representation levels, AHR was selected for validation due to its comparable representation pattern in both metastatic tumors that were analyzed." (PMID 33214553, 2020).
pancreatitis (3 papers, 2021 to 2024). Inflammation of the pancreas. "Resveratrol, an AHR antagonist, prevents the harmful effects of pancreatitis and mitigates mitochondrial damage." (PMID 38612627, 2024).
periodontal disease (3 papers, 2015 to 2024). "The attenuation of this periodontal disease may correlate with the regulation of AhR/NF-κB/NLRP3 inflammasome pathway by VD3." (PMID 31691738, 2019).
prostate (3 papers, 2010 to 2025). "In the current study, AhR, as a ligand-activated transcription factor, was found to be involved in prostate carcinogenesis through genomic and epigenetic modifications." (PMID 38410974, 2024). "Moreover, the AhR acts as an E3 ligase of the AR and AhR null TRAMP mice show increased prostate tumorigenesis." (PMID 20140206, 2010).
prostate tumors (3 papers, 2019 to 2025). "High concentrations of tryptophan in prostate tumours lead to elevated levels of kynurenine, a terminal product of tryptophan metabolism which binds to and activates the aryl hydrocarbon receptor (AHR)." (PMID 39859489, 2025). "Interestingly, the positive correlation between AR and PARP7 expression appears to be lost in metastatic prostate tumors, suggesting that PARP7 becomes highly dependent on AHR signaling for its expression in advanced disease." (PMID 37077937, 2023).
rosacea (3 papers, 2023). A chronic erythematous skin disorder that affects the face. "Benvitimod, an AhR agonist, activates AhR, leading to alleviation of rosacea-like eruptions in female BALB/c mice skin." (PMID 36983027, 2023). "AhR-modulating drugs can reduce macrophage activation and inflammation in rosacea by targeting the skin’s response to environmental toxins." (PMID 37691916, 2023). "Tapinarof, an innovative topical treatment acting as an AhR agonist, holds promise in treating rosacea." (PMID 37691916, 2023). "Therefore, it is shown that AhR activation can be a positive target for treating rosacea." (PMID 36983027, 2023).
tuberculosis (3 papers, 2024 to 2025). A chronic, recurrent infection caused by the bacterium Mycobacterium tuberculosis. "In the field of tuberculosis, researchers have identified a significant role for AhR in the death of macrophages infected with Mtb via the use of CRISPR interference screening technology." (PMID 39438693, 2024). "Given that the delay in the T-cell response is a major barrier to curing Mtb infection and one of the bottlenecks in the development of new tuberculosis vaccines, our findings provide important theoretical support for the development of host-directed therapeutic strategies that target AhR." (PMID 39438693, 2024). "In tuberculosis patients, overactivation of the Kyn-AhR pathway may increase the number or proportion of Tregs in the lymph nodes or lungs, which suppresses the infiltration and function of effector T cells in the lungs." (PMID 39438693, 2024). "Inhibiting AhR activity could help accelerate the immune response of T cells, thereby enhancing the host’s control over Mtb infection and opening new avenues for the treatment and vaccine development of tuberculosis." (PMID 39438693, 2024). "Here, AhR activation via kynurenine lead to inhibition of the JAK/STAT1 pathway and limited T cell recruitment and both AhR and IDO1 have been suggested as potential therapeutic targets for Tuberculosis." (PMID 40293552, 2025). "In contrast, in mice lacking the AhR in macrophages, we observed a significant increase in T-cell infiltration, along with increased cytokine secretion by CD4+ and CD8+ T cells, ultimately promoting an adaptive immune response against tuberculosis and reducing the bacterial load." (PMID 39438693, 2024).
Ureteral obstruction (3 papers, 2022 to 2024). Obstruction of the flow of urine through the ureter. "For example, in a mouse model of unilateral ureteral obstruction, AHR activation was shown to exacerbate renal inflammation and fibrosis, whereas AHR deficiency attenuated these pathological changes." (PMID 37510393, 2023).
vulvovaginal candidiasis (3 papers, 2014 to 2020). Infection of the vulva and vagina with a fungus of the genus CANDIDA. "Interestingly, in a model of murine vulvovaginal candidiasis an increased expression of AhR was observed in the vagina of both naïve and infected IDO1-deficient mice, suggesting a further mechanism of mutual transcriptional regulation between IDO1, the source of l-kyn, and its sensor AhR." (PMID 25360135, 2014).
abortion (2 papers, 2023 to 2026). the ending of pregnancy by removing a fetus or embryo before it can survive outside the uterus. "In vivo, excessive administration of KYN in pregnant mice increases the rate of embryo resorption, whereas pharmacological inhibition of AHR partially attenuates cGAS-STING pathway activation in dMφs and ameliorates fetal loss in an abortion-prone mouse model." (PMID 41522347, 2026). "Most notably, AHR (cg25577322) is upregulated in decidual natural killer cells in women with recurrent spontaneous abortion and was hypomethylated in parous women in our study." (PMID 36765422, 2023).
alcoholic hepatitis (2 papers, 2022 to 2023). Acute hepatitis resulting from ingestion of alcohol. "The Lactobacillus–tryptophan–AhR axis has been reported to mediate intestinal homeostasis, and to affect immunoregulatory T cells and the improvement of alcoholic hepatitis." (PMID 37764239, 2023).
allergic rhinitis (2 papers, 2022 to 2025). Inflammation of the nasal mucous membranes caused by an IgE-mediated response to external allergens. "It has been found that Di(2-ethylhexyl) phthalate (DEHP), a plasticizer, boosts the ovalbumin-induced allergic rhinitis by activating the AhR canonical pathway." (PMID 36601108, 2022). "Our prior investigations elucidated that PM2.5 and di(2-ethylhexyl) phthalate (DEHP) activated the AhR within the nasal mucosa, disrupting the nasal mucosal epithelial barrier and contributing to CRS and allergic rhinitis." (PMID 40559961, 2025).
autism (2 papers, 2019 to 2021). Persistent deficits in social interaction and communication and interaction as well as a markedly restricted repertoire of activity and interest as well as repetitive patterns of behavior. "A handful of animal studies has linked environmental pollutants to autism-like behavior through the AhR pathway." (PMID 34502168, 2021). "The interplay between genetics and environmental factors, mediated by AhR, and the cause for autism raises the question of how exactly changes in the AhR pathway is capable of contributing to ASD." (PMID 34502168, 2021). "This section discusses the most recent studies and evidence for the role and impact of epigenesis and polymorphism of AhR and regulated genes in autism development and risk." (PMID 34502168, 2021). "IL6 has been linked to the pathogenesis of autism since it is involved in the homeostasis between neuro- and gliogenesis and is synergistically induced by xenobiotics, the kynurenine pathway and by the Aryl Hydrocarbon Receptor (AHR)." (PMID 31578139, 2019). "Toxicities of environmental pollutants, including PCBs and dioxins on autism, have been well characterized to be regulated by the AhR/CYP1 pathway, leading to the induction of a wide range of genes that express XREs on their promoters." (PMID 34502168, 2021). "The next part of the review discusses recent advances and studies, highlighting the impact and role of the AhR pathway in the incidence of autism." (PMID 34502168, 2021). "Since these environmental toxicants target AhR to mediate their toxicities, it is highly possible that AhR could play a role in autism development during childhood; however, the links between AhR and autism are still not fully revealed." (PMID 34502168, 2021). "In addition, activation of the AhR/CYP1 results in DNA adduct formation and DNA strand breakage, considered as risk factors for the development of autism." (PMID 34502168, 2021). "Examining AhR and its role in autism may prove beneficial in understanding the etiology of the disease with deeper comprehension." (PMID 34502168, 2021). "Impact of epigenetic and polymorphic changes by AhR/CYP1 on autism." (PMID 34502168, 2021). "Additionally, the current review sheds light on some novel, postulated AhR-mediated mechanisms for drugs that are currently used in autism." (PMID 34502168, 2021). "Importantly, these POPs and PAHs are known to exhibit their toxic effects on the human body through the activation of a cytosolic protein known as the aryl hydrocarbon receptor (AhR), suggesting high possibility that the AhR pathway could mediate increased autism development and incidence." (PMID 34502168, 2021). "This section summarizes the most recent human and experimental studies and evidence for the potential role of AhR and its regulated genes, CYP1A1, CYP1B1, and CYP1A2 on autism development." (PMID 34502168, 2021). "Evidence suggests the link between the AhR pathway and autism severity; however, few (to no) studies have been carried out to explore this possibility." (PMID 34502168, 2021). "However, the regulation of miRNAs by the AhR/CYP1 pathway was not investigated in autism and warrants further investigation." (PMID 34502168, 2021). "What supports this possibility is that AhR and its regulated genes, CYP1A1, CYP1A2, and CYP1B1, are highly and constitutively expressed in the placenta, which may be activated by exposure to environmental toxicants during pregnancy and, hence, increase the incidence of autism." (PMID 34502168, 2021).
B-cell lymphoma (2 papers, 2014 to 2025). "Furthermore, expression analysis of human B-cell lymphomas revealed a correlation of AHR and AHR target gene expression with IDO1." (PMID 24657910, 2014). "In human B-cell lymphoma IL-6 expression correlated with AHR expression." (PMID 24657910, 2014).
bladder tumor (2 papers, 2025). "Among them, 13 genes, including AHR, BCL2L1, CCND1, KRAS, SOX4, MYC, and E2F family genes, were previously reported to have increased expression in BC tissue, and their alterations, either through amplification or upregulation, are linked with bladder tumor initiation or progression." (PMID 40801146, 2025).
cecal cancer (2 papers, 2024). "Furthermore, AhR functions as a tumor suppressor in liver carcinogenesis, and reduced AhR expression has been observed in human cecal cancer tissues and adjacent areas." (PMID 39767818, 2024).
chronic asthma (2 papers, 2021 to 2022). An asthma that is characterized by the development of persistent airway inflammation and recurrent attacks of breathlessness and wheezing, which vary in severity and frequency. "Our results confirm a recent study showing enhanced AAI and remodeling in an ovalbumin-induced chronic asthma model using AhR-/- compared to WT mice and complete the picture adding the role of the CYP1 gene family." (PMID 35734174, 2022).
chronic lung disease (2 papers, 2021). According to the definitions of the American and British Thoracic Societies, including pulmonary functional tests, X-rays, and CT scans for items such as fibrosis, bronchiectasis, bullae, emphysema, nodular or lymphomatous abnormalities. "Further investigation of the precise mechanisms by which the AhR exerts is protective functions may lead to the development of therapeutic agents to treat people with chronic lung diseases that have an inflammatory etiology, but for which few therapeutic options exist." (PMID 33659010, 2021).
chronic pancreatitis (2 papers, 2022 to 2024). A chronic inflammatory process causing damage and fibrosis of the pancreatic parenchyma. "Cigarette smoke—a significant risk factor for chronic pancreatitis—contains elevated levels of dioxin-like compounds that activate aryl hydrocarbon receptor (AHR) signaling." (PMID 38612627, 2024). "A study comparing the mRNA expression of AhR in normal pancreas and chronic pancreatitis demonstrated a 2.8-fold higher AhR expression in the acinar and ductal cells of chronic pancreatitis tissues than in normal pancreas." (PMID 36418969, 2022).
Cirrhosis (2 papers, 2013 to 2016). A chronic disorder of the liver in which liver tissue becomes scarred and is partially replaced by regenerative nodules and fibrotic tissue resulting in loss of liver function. "Moreover, the simultaneous assessment of mRNA and protein expressions of CYP1A enzymes and AhR has, at least in part, clarified the mechanism responsible for the cirrhosis-associated decrease of inducibility." (PMID 23626760, 2013).
clear cell carcinoma (2 papers, 2019 to 2020). "When comparing cytoplasmic AhR expression between the different histological subtypes, it becomes apparent that the clear cell carcinoma shows higher IR scores (median IRS = 8 with a range of 4–8; p = 0.077)." (PMID 31212758, 2019). "However, AhR activation by AF has to be confirmed in future studies using other papillary and clear cell carcinoma tumors." (PMID 32443455, 2020).
co-infection (2 papers, 2023 to 2025). "The gizzard worms also cause co-infection with A. galli in chickens; thus, the development of AhR against PPZ in C. hamulosa is not surprising." (PMID 40143768, 2025). "However, it has been reported that both infections involve different proinflammatory cascades such as CCL4 and AhR, which can perpetuate and exacerbate the clinical presentation of SARS-CoV-2 and DENV co-infection." (PMID 37580025, 2023).
cognitive decline (2 papers, 2025). "Supplementation with B.p improves aging‐related cognitive decline and prevents microglia engulfment of synapses via activation of IAA/AHR signaling." (PMID 40219707, 2025).
colorectal adenocarcinoma (2 papers, 2022 to 2024). The most common type of colorectal carcinoma. "We next examined whether PARP7 knockdown would result in increased AHR signaling in Caco2 cells, a human colorectal adenocarcinoma cell line." (PMID 35055106, 2022).
Cushing syndrome (2 papers, 2023 to 2024). Cushing's syndrome (CS) encompasses a group of hormonal disorders caused by prolonged and high exposure levels to glucocorticoids that can be of either endogenous (adrenal cortex production) or exogenous (iatrogenic) origin. "It is also worth recalling that ketoconazole––a widely used agent for Cushing’s syndrome––is itself an aromatic hydrocarbon and, in addition to its action on the first and last step of steroidogenesis, interacts with the AHR complex and activates hepatic AHR-dependent gene transcription." (PMID 38637430, 2024). "Apart from PRKAR1A variants in the subset of cyclical Cushing’s syndrome related to primary pigmented nodular adrenocortical disease and a case study raising a putative link between AHR and cyclical Cushing’s disease, there are currently no genes implicated in cyclical Cushing’s syndrome." (PMID 38075079, 2023).
cutaneous melanoma (2 papers, 2021 to 2026). A primary melanoma arising from atypical melanocytes in the skin. "The authors demonstrate that AHR transactivates CIITA, thereby up-regulating antigen-presenting HLA-II molecules in cutaneous melanoma." (PMID 41964090, 2026). "As anticipated, a lung-specific AhR-correlated signature was not discriminative in terms of survival for patients with other tumors, such as skin cutaneous melanoma (SKCM), or transposable to all tumors." (PMID 33451095, 2021).
cyst (2 papers, 2017 to 2019). A sac-like closed membranous structure that may be empty or contain fluid or amorphous material. "In some instances, we detected cysts with 32 trophocytes suggesting that AHR activation led to an extra round of mitosis during cyst formation." (PMID 29262535, 2017).
demyelinating disease (2 papers, 2017 to 2023). A broad group of disorders that affect the myelin sheaths that cover the neurons. "Taken together, our study provides a promising strategy for targeting AhR in microglia for the therapies of CNS demyelinating diseases." (PMID 36966295, 2023). "Altogether, our study highlights an essential role for AhR in microglial phagocytic function and suggests the therapeutic potential of AhR in demyelinating diseases." (PMID 36966295, 2023). "It identifies a mechanism by which environmental pollutants might influence CNS myelination and suggest AhR as a relevant drug target for demyelinating diseases." (PMID 28851966, 2017).